ALDH1A1 (aldehyde dehydrogenase 1 family member A1)
Diseases named in the same sentence as ALDH1A1 in open-access papers (continued):
Sharing a sentence is not in itself a finding about the gene and the disease.
tumor (continued). "Here, we found that BMI1, CD44, SOX2, OCT4, UBE2C, CXCR4 CSCs marker genes are significantly upregulated, while IGF1-R, KLF4, ALDH1A1, CD133, FAM3C are downregulated in the tumor core vs healthy mucosa of 24 patients with OSCC." (PMID 38096163, 2023). "These analyses showed that mEER SRE:CD63-eGFP cells carried on average 30 LV copies per cell (CpC), and that 5 CpC were detected in mEER ALDH1A1:CD63-eGFP cells, indicating full transduction of the tumor cell populations." (PMID 36735677, 2023). "The expression levels of CSC markers, such as ALDH1A1, EpCAM, CD133, CD44V6, and CD44V8-10, were confirmed in the tumor tissues of patients with CCA using IHC staining." (PMID 35223723, 2022). "In fact, ALDH1A1-specific CD8+ T cells lysed ALDH+ cells, inhibiting tumor progression, and metastasis, and increasing the rate of survival of xenograft-bearing immunodeficient mice." (PMID 35982868, 2022). "Higher expression level of CSC markers including ALDH1A1, CD44, and CD133 was also reported in tumor tissues collected immediately after primary chemotherapy compared with paired primary samples from EOC patients." (PMID 35401749, 2022). "Intratumoral Fn injection led to an increase of formate levels within tumour interstital fluids (TIFs), accompanied by an increased AHR, CYP1B1, SOX2 and ALDH1A1 (trendwise) gene expression." (PMID 35437333, 2022). "In an attempt to characterize the effect of lncRNA ROR and its downstream pathway TESC/ALDH1A1/TUBB3/PTEN axis on PTC in vivo, transduced TPC-1 and BCPAP cells were subcutaneously inoculated into BALB/c nude mice to construct a PTC tumor-bearing model." (PMID 35173149, 2022). "The expression levels of CSC markers, such as ALDH1A1, EpCAM, CD133, CD44V6, and CD44V8-10, were determined in the tumor tissues through IHC staining." (PMID 35223723, 2022). "PTC tumor and adjacent tissues were obtained, followed by measurement of lncRNA ROR and TESC, ALDH1A1, and TUBB3 expression." (PMID 35173149, 2022). "Progestin and adipoQ receptor 3 is downregulated and negatively related to tumor size, stage, and OS in GC, and its overexpression in BGC-823 cells leads to decreased ALDH1A1 expression." (PMID 35310914, 2022). "Parallel to our finding, ALDH1A1 displayed notably higher expression in PTC tissues than in normal tissues and had a positive correlation with the tumor stage and size." (PMID 35173149, 2022). "Another group of researchers reported that the ALDH1A1 inhibitor disulfiram and chemotherapeutic agent gemcitabine cooperatively inhibited breast tumor growth and tumorigenesis by purging ALDH+ tumor-initiating cells and activating T-cell immunity." (PMID 35814382, 2022). "We have earlier shown that DsRed2+ cells have higher ALDH1A1 expression, the activity of ALDH, expression of pluripotency markers, soft agar colony formation efficiency, and tumor initiation capacity." (PMID 35004310, 2021). "The study suggested the cooperation of EZH2 and BRCA1 in regulating ALDH1A1 expression, PCa stem cells, and tumor radioresistance, and the genetic silencing of EZH2 alone or in combination with BRCA1 knockdown decreased the ALDH1A1 level." (PMID 34572930, 2021). "In contrast, ALDH1A1 expression in stromal cells was frequently observed in tumors with high levels of luminal cytokeratins CK8/18 and rarely found in tumor specimens with epithelial-mesenchymal transition (EMT) phenotype." (PMID 34572930, 2021). "ALDH1A1 was expressed in six out of nine tumors; ALDH1A2 was also expressed in six out of nine tumor samples, and ALDH1A3 was present in only one out of nine tumors examined." (PMID 34572134, 2021). "The p-AXL levels were well correlated with the ALDH1A1 and SLUG levels in the tumours, with r values of 0.87 and 0.65." (PMID 32051483, 2020). "Oral administration of EGCG and green tea extract (GTE) inhibited tumour growth in mice and reduced p-AXL, ALDH1A1, and SLUG in tumours." (PMID 32051483, 2020).
tumor (continued). "Accordingly, ALDH1A1 is a CSC marker of many tumors, but it is also expressed in tumor cells in a more differentiated state, characterized by lower or limited proliferative potential." (PMID 35582039, 2020). "In addition, the expression level of ALDH1A1 could be used to classify tumor staging." (PMID 32039729, 2020). "In tumor immunity, the ALDH1 family (including ALDH1A1, ALDH1A2, and ALDH1A3) converts retinal to RA, which promotes the induction, function and stability of regulatory T cells, leading to immune tolerance that compromises tumor immunity." (PMID 32140062, 2020). "In this regard, a study showed that miR-23b was down-regulated in Hela and CaSki cervical cancer stem cells (CCSCs) derived from tumor spheres and that miR-23b directly binds to the 3′UTR of ALDH1A1 to suppress its translation." (PMID 30842790, 2019). "Immunoblot analysis of tumour lysates showed that tumours developed from stem‐like HepG2SF1 cells had increased expression of AFP, CD133 and ALDH1A1 as well as upregulation of the Akt/mTOR axis and lower expression of pAMPK, AMPK, pACC and ACC." (PMID 30959553, 2019). "ALDH1A1 and ALDH1A3 regulate cellular function in both normal stem cells and tumor-initiating stem-like cells, promoting tumor growth and resistance to drugs and radiation." (PMID 30733805, 2019). "Next, we screened blood samples from a non-tumor cohort of 26 patients and 45 NSCLC patients with different disease stages for the presence of ALDH1A1 and global ALDH." (PMID 31534455, 2019). "These mice were treated with either Dox to induce DDB2 knockdown in xenograft tumor cells, or/and NCT-501 to inhibit the activity of ALDH1A1." (PMID 29752431, 2018). "We therefore conducted immunohistochemical analyses of ALDH1A1 levels in patient-derived primary CRC tissue and corresponding liver metastases in relation to tumor characteristics and clinical parameters." (PMID 30308036, 2018). "In mice bearing MCF-7 ALDH1A1KD cells, tumor growth and mass were significantly reduced, compared to MCF-7 Scr and MCF-7 ALDH1A1+." (PMID 30541574, 2018). "We further showed that treatment with a selective ALDH1A1 inhibitor blocked DDB2 silencing-induced expansion of CSCs, and halted orthotopic xenograft tumor growth." (PMID 29752431, 2018). "In conclusion, ALDH1A1 expression in primary tumors and liver metastases identifies a subset of CRC tumors with poorly differentiated histology, right-sided tumor location and poor prognosis." (PMID 30308036, 2018). "Collectively, these results suggest that this newly characterized GSH/DHLA-dependent NAD+-reduction activity of ALDH1A1 can decrease cellular NAD+/NADH ratio and promote tumor growth." (PMID 28978015, 2017). "Expressions of SOX2, OCT4, WNT, NANOG, ABCG2 and ALDH1A1 was assessed both at transcriptional and translational levels from spheroids and sorted populations of CD44+/24− and ALDH+ cells of CT-TNBC tumor (CSC) versus the whole tumor." (PMID 28835684, 2017). "To further test if artificially increasing the NAD+/NADH ratio is sufficient to inhibit tumor growth, we expressed an NADH oxidase from Lactobacillus brevis (LbNOX) in DKO_1A1 (ALDH1A1/3A1 double knockout rescued with ALDH1A1) cells." (PMID 28978015, 2017). "Although numerous studies have classified both ALDH1A1 and ALDH1A3 as markers of CSCs derived from several distinct tumor types, the functional roles of these enzymes in CSCs have not been well-defined." (PMID 28423611, 2017). "Tumor formation in vivo was observed in the majority of mice (4 out 5) when E10-TAZ-S89A-T cells were injected, whereas knockout of Aldh1a1 in E10-TAZ-S89A-T cells (E10-TAZ-S89A-sgAdhl1a1) completely abolished tumor seeding and growth in mice." (PMID 28415606, 2017). "Beside ALDH1A1 and SOX2, other molecules such as DKK1 and NOTCH1 were notably upregulated in CSCs during tumor progression." (PMID 27292183, 2016). "IHC staining of tumour tissues confirmed knockdown of SAE2 level and reduced levels of CSC markers (ALDH1A1 and CD44)." (PMID 27465491, 2016).
tumor (continued). "Consistent with SAE2 knockdown, IHC staining of tumours in the shSAE2 group showed reduced level of SAE2, as well as reduced level of the CSC markers ALDH1A1 (an isoform believed to be critical for ALDH activity in CSCs30) and CD44, relative to shCtrl cells." (PMID 27465491, 2016). "SP cells showed higher tumor-initiating ability and SP cell showed higher expressions of stem cell-related genes including SOX2, ALDH1A1, KLF4 and NANOG, indicating that SP cells are enriched with CSCs/CICs." (PMID 27418136, 2016). "Several factors related with the CSC phenotype, such as ALDH1A1, SOX2, DKK1 and NOTCH1, were increasingly upregulated in the emerging CSC subpopulations during tumor progression." (PMID 27292183, 2016). "We found that SOX2 is expressed at high level in SP/ALDHBr cells, and knockdown of SOX2 suppressed the expressions of ALDH1A1 and ABCG2, and suppressed tumor-initiation." (PMID 23967051, 2013). "Based on these premises, in order to characterize the expression of putative stem markers during the early phases of carcinogenesis, we studied the expression of LGR-5, MSI-1, DCAMKL-1, CD133 and ALDH1-A1 in both MDF and tumours by immunohistochemistry." (PMID 23374535, 2013). "To further evaluate the interaction between ALDH1A1-siRNA and GEM, we determined the half maximal inhibitory concentration (IC50) and found strong synergistic anti-tumor effects." (PMID 22710732, 2012). "Minichromosome Maintenance Complex Component 10 (MCM10), overexpressed 4.2-fold in resistant tumors, activates Aldehyde Dehydrogenase 1 Family Member A1(ALDH1A1) and SRY-Box Transcription Factor 2 (SOX2) to promote stemness, evidenced by tumor sphere enlargement." (PMID 40977684, 2025). "At the same time, it also promoted the expression of ALDH1A1 and tumor stemness, while inhibiting CXCR2 or NF-κB could block the tumor promotion effect of IL-8." (PMID 40008905, 2025). "The elevated lactate levels in tumor cells expressing ALDH1A1 and S100A4 from the resistant group, along with the increased expression of ALDH1A1, suggest that lactylation is integral to the development of drug resistance, resulting in a higher accumulation of lactate products in this group." (PMID 40093000, 2025). "This underscores the importance of accounting for tumor heterogeneity when targeting ALDH1A1, as certain TNBC subpopulations may rely more heavily on ALDH1A1 function." (PMID 40076923, 2025). "Another study on the function of the ARID1A gene in ICC cells elucidated that individuals with ALDH1A1 positivity had a poorer prognosis, suggesting that ARID1A inhibition of ALDH1A1 expression could play a role in tumor suppression." (PMID 40008905, 2025). "Furthermore, ALDH1A1 protein expression was upregulated in LUAD and positively correlated with tumor stage (P = 0.020) and distant metastasis (P = 0.006)." (PMID 40886002, 2025). "The IHC results showed that inhibiting ALDH1A1 or inhibiting IL-8/CXCR2 could suppress the expression of NF-κB and promote apoptosis of tumor cells." (PMID 40008905, 2025). "While ALDH1A1 negatively correlates with AR target genes in noncancerous prostate epithelium, this mutual exclusivity reduces upon tumor development." (PMID 38169509, 2024). "Tumor stem cell (CSC) pluripotency markers include CD133, ABCG2, and ALDH1A1." (PMID 38576495, 2024). "In the lung sections the expression levels of SOX2 and ALDH1A1 were high in the non-tumor area, relative to the levels in the tumor in both the PLGA-PEI-si-NT and PLGA-PEI-si-m/hVDAC1-B-treated groups." (PMID 39272828, 2024). "We then tested whether ALDH1A1 and ALDH1A3 regulate tumor cells homing to bone and bone marrow colonization in vivo." (PMID 38169509, 2024). "In a previous in vitro investigation, patient‐derived BC cells isolated from an ER+ tumor exhibited CSC‐like properties and, displayed high expression of pluripotency markers and ALDH1A1, rendering them resistant to hormonal interventions as well as antihormonal medications." (PMID 38400679, 2024).
tumor (continued). "The protein expression of ALDH1A1, ZBTB7B, and PD-L1 was evaluated in tumor biopsy tissue." (PMID 39107297, 2024). "Finally, after conducting additional verification of patient tissue and clinical data, we have confirmed the potential translational value of targeting ALDH1A1 and ZBTB7B for tumor immunotherapy." (PMID 39107297, 2024). "Moreover, we performed the same evaluation for tumor cells upon knockdown of CTNNB1, which has been shown to positively regulate ALDH1A1 expression." (PMID 38169509, 2024). "The role of ALDH1A1 and CD44 in OS as biologic markers of a subset of tumor cells that may confer treatment resistance has yet to be clinically evaluated or validated." (PMID 38371078, 2024). "ALDH1A1 has been found to effectively increase NADH levels and promote tumor growth." (PMID 36450445, 2023). "Of note, mSca is ubiquitously expressed by all tumor cells under the control of a constitutive bi-directional promoter, along with CD63-eGFP, whereas SrtA is specifically expressed by CSC under the regulation of the ALDH1A1 promoter." (PMID 36735677, 2023). "The levels of ALDH1A1 mRNA in tumor and non-tumor tissues were not substantially different, according to an RT-PCR analysis of 47 patient samples of HCC tumorous and their respective adjacent non-tumorous tissues." (PMID 37686694, 2023). "Consequently, our study revealed that lncRNA ROR promotes the cell malignant behaviors and tumor growth of PTC, which is achieved in part by the TESC/ALDH1A1/TUBB3/PTEN axis." (PMID 35173149, 2022). "The so-called inflammatory CAFs (iCAFs) that express ALDH1A1, KLF4, LEPR, and CXCL12 were distributed across the areas that contain both tumor and immune-stromal cells, whereas the myofibroblast CAFs were enriched only in the tumor cell-enriched area." (PMID 36376874, 2022). "Expectedly based on these data, our experiment on SOC tissue samples demonstrated higher expression of SALL4 in tumor tissues rather than normal tissue samples while the expression of ALDH1A1 protein reduced in tumor tissues in comparison to normal tissues." (PMID 35090523, 2022). "This migratory behavior may be enhanced following concomitant expression of ALDH1A1 and CD36 expression induced by environmental factors, such as rich LPA present within the tumor microenvironment." (PMID 36497140, 2022). "Among ALDH1A1 selective inhibitors, a potent theophylline-based molecule, called NCT-501, has demonstrated in vitro efficacy on chemotherapy-resistant ovarian and HNSCC cell lines and reduction of tumor growth in vivo." (PMID 35299840, 2022). "Significant differences were found in tumor sizes between the ALDH1A1 positive and ALDH1A1 negative groups." (PMID 34778599, 2021). "Analysis of the tumor microenvironment regulating CSCs revealed that the factors in CSC-niche activates effector molecules that function as CSC markers, including pluripotency markers, CD133, ABCG2 and ALDH1A1." (PMID 33968778, 2021). "Intriguingly, ALDH1A1+-BCSCs tended to be localized to the arteriolar niche rather than in the tumor nest." (PMID 34168243, 2021). "Taken together, the higher number of ALDH1A1 and VEGFR2 colocalizing tumor cells in HPV-positive OPSCC might indicate that these tumors are associated with a higher number of migratory CSCs." (PMID 34680369, 2021). "Furthermore, this inhibitor has shown other interesting roles for tumor inhibition, like down-regulation of KIF11 and ALDH1-A1, particularly when combined with existing treatments." (PMID 34548908, 2021). "In the ER+ tumours, BMI1 maintained similar associations and showed negative correlation with ALDH1A1 (P = 0.005) and CD133 (P = 0.001)." (PMID 32524353, 2020). "Our findings indicate that combinatorial treatment of ATRA with gefitinib could reduce CSC-mediated resistance by down-regulating expression of ALDH1A1 and CD44 and potentiate the anti-tumor effect of gefitinib in NSCLC/ADC." (PMID 32293355, 2020).
tumor (continued). "Also, PTC cells with DOCK9-AS2 knockdown presented restrained tumor sphere forming efficiency and lowered levels of stemness-related proteins including CD133, Nanog, OCT4, SOX2, EpCAM, and ALDH1A1." (PMID 32917852, 2020). "Contrarily, NOTCH signaling pathway increased ALDH1A1 Lys-353 deacetylation at a post-translational level through the induction of silent information regulator 2 (SIRT2) expression, promoting tumorigenesis and tumor growth in a BC model." (PMID 33584277, 2020). "We further checked the protein expression of TRIB3, ALDH1A1, and c-MYC in lysates of xenografted tumors and results showed that TRIB3 was slightly decreased in the only one small engrafted tumor of TRIB3-knockdown AN3CA cells, while the expression levels of ALDH1A1 and c-MYC were greatly reduced." (PMID 33334065, 2020). "Furthermore, high AXL and p-AXL levels in the AXL-high clone strongly induced the tumourigenicity of H1299 cells in SCID/Beige mice, and oral administration of EGCG + GTE inhibited the tumour growth of H1299 cells by reducing p-AXL, SLUG and ALDH1A1 levels." (PMID 32051483, 2020). "CSCs are more resistant to conventional chemotherapy than the more differentiated tumor cells and can be identified by the expression of immaturity markers such as cluster of differentiation 44 (CD44) and aldehyde dehydrogenase 1 family member A1 (ALDH1A1) in GC." (PMID 32545795, 2020). "Similarly, the inhibitory effect of ATRA on ALDH1 was confirmed in our system: ATRA effectively reduced ALDH1A1 expression and inhibited CSC marker expression, tumor growth, and colony/sphere formation." (PMID 30166520, 2018). "In line with this possibility, our findings suggest that aggressive tumor cells with increased expression of PTOV1, ALDH1A1, and CCNG2 might correspond to potential CSCs with great capacity to metastasize and higher resistance to docetaxel." (PMID 28938627, 2017). "As have demonstrated that ALDH1A1 can decrease the cellular NAD+/NADH ratio, we wondered whether ALDH1A1 promotes tumor growth via decreasing the NAD+/NADH ratio." (PMID 28978015, 2017). "In addition, tumor expression of IL-6, MMP-9 and ALDH1A1 was decreased (P < 0.05) in mice treated with pHLIP-PNA3 compared to control." (PMID 28420874, 2017). "Additional studies have reported that ALDH1A1, ALDH7A1, ALDH2 and/or ALDH1A2 are responsible for driving Aldefluor® activity in other tumor types, indicating that the ALDH isoform(s) responsible for Aldefluor® activity may be tumor-specific." (PMID 28937653, 2017). "Interestingly, the expression of 84 stem cell genes within different GBM regions reveals that the invasive region has the highest ALDH1A1 and ABCG2 expression as compared to other tumour regions." (PMID 29156557, 2017). "Consequently, SOX2 was silenced in mammospheres, formed from human tumor tissues which resulted in down regulation of OCT4, NANOG, ALDH1A1, and most importantly, ABCG2 expression (p < 0.01), confirming a direct correlation of SOX2 with ABCG2." (PMID 28835684, 2017). "We showed that inactivation of Aldh1a1 by its inhibitor or CRISPR (Clustered Regularly-Interspaced Panlindromic Repeat) gene editing can block TAZ-induced lung tumorigenic and CSC phenotypes in vitro and tumor formation in vivo." (PMID 28415606, 2017). "In contrast, strong immunoreactivities of ALDH1A1 and CD44V6 were observed in the tumor cells (c)." (PMID 27647953, 2016). "ALDH1A1 was expressed very heterogeneously and non-uniformly within the tumor tissue of HCC specimens." (PMID 26783961, 2016). "In addition, other studies have found enzymatic participation of ALDH1A1, 1A2, 1A3, 2, 7A1 and 8 in the ALDEFLUORTM assay in other tumor types." (PMID 26445849, 2016). "Interestingly, the NB1-C cell line and the related NB1-PDX tumor displayed a similar expression pattern of ALDH1 isoenzymes, with elevated expression levels of ALDH1A1 and A3." (PMID 27724856, 2016).